NR0B1 (nuclear receptor subfamily 0 group B member 1)
Diseases named in the same sentence as NR0B1 in open-access papers (continued):
Sharing a sentence is not in itself a finding about the gene and the disease.
Ewing sarcoma (26 papers, 2012 to 2025). A small round cell tumor that lacks morphologic, immunohistochemical, and electron microscopic evidence of neuroectodermal differentiation. "It has been demonstrated that DAX1 (NR0B1), an orphan nuclear receptor, is induced by the EWS/FLI1 oncoprotein and is highly expressed in Ewing’s tumors, suggesting that DAX1 is a biologically relevant target of EWS/FLI1-mediated oncogenesis." (PMID 37298283, 2023). "NR0B1 has also been confirmed to be related to the occurrence and development of a variety of tumors, for example, the transformed phenotype of Ewing's sarcoma requires sustained NR0B1 expression." (PMID 37316840, 2023). "NR0B1 suppression by NKX2-2 contributes to the maintenance of an undifferentiated state in Ewing sarcoma cells." (PMID 37894854, 2023). "mRNA expression of PPP1R1A, GLI1, FoxM1, and NR0B1 genes highly expressed in Ewing’s sarcoma cells was dependent on EWS-FLI1." (PMID 36194562, 2022). "As example, the transcription factors NR0B1 and NKX2-2 are well-known to be associated with Ewing Sarcoma." (PMID 33924679, 2021). "Epigenetic modification of NR0B1 leads to its ectopic activation in Ewing's sarcoma and lung cancer, enabling it to promote cancer cell proliferation." (PMID 33407546, 2021). "In Ewing sarcoma tumors, NR0B1 microsatellites ranged in size from small, two-segment repeats containing 16 GGAA motifs to larger multisegment repeats containing up to 61 GGAA motifs." (PMID 25093581, 2014). "Given the markedly different incidence of Ewing sarcoma in these populations and the role of the NR0B1 protein in sustaining the oncogenic phenotype of Ewing sarcoma, we elected to focus on NR0B1 for this study." (PMID 25093581, 2014). "EWS-FLI1 knockdown based studies and transcriptional profiling data of various Ewing’s sarcoma cell lines have shown that gene like NR0B1, NKX2.2, EZH2, GLI1 are up regulated by EWS-FLI1." (PMID 23145994, 2012). "Additional functional assessments have shown that in patient-derived Ewing sarcoma cell lines, dysregulated NR0B1 expression is necessary for oncogenic transformation." (PMID 24704979, 2012). "We identified 88 transcription factors, many of which have been described previously as part of the core regulatory transcription factor circuitry in specific cancer types, such as PHOX2B, TWIST1, and ISL1 in neuroblastoma; MYOD1 and MYOG in rhabdomyosarcoma; NR0B1 in Ewing sarcoma." (PMID 34818552, 2021). "To investigate if GGAA-microsatellite polymorphisms influenced NR0B1 gene expression in Ewing sarcoma tumors, we quantified normalized NR0B1 expression using microarray data from 31 Ewing sarcoma samples from which both PCR sequencing data and RNA were available." (PMID 25093581, 2014). "The GGAA-microsatellite of two critical upregulated EWS/FLI-targets in Ewing sarcoma (NR0B1 and CAV1) have been shown to be highly polymorphic in African and white European populations, with a predisposition for significantly larger GGAA-microsatellites in Africans, especially at the NR0B1 locus." (PMID 25093581, 2014). "Additionally, ectopic EWS/FLI expression in murine-derived NIH3T3 cells does not upregulate Nr0b1, further supporting observation that GGAA-microsatellites are necessary for regulation of Nr0b1 in Ewing sarcoma." (PMID 25093581, 2014). "Our research group has predominantly focused on looking up genes regulated positively or negatively by EWSR1::FLI1 in Ewing sarcoma cells (e.g., NR0B1/DAX1, CCK, LOX, SPRY1, DKK2, or FEZF1)." (PMID 37511533, 2023). "NR0B1 is a target of EWSR1-FLI1 that directly modulates transcription and oncogenesis in Ewing sarcoma." (PMID 35285802, 2022). "The nuclear receptor NR0B1 and the homeobox transcription factor NKX2-2 were up-regulated in Ewing’s sarcoma." (PMID 36194562, 2022). "Some of these transcription factors, such as NR0B1 or BCL11B, have been previously shown to be regulated by EWSR1-FLI1 and play important functional roles in Ewing sarcoma pathogenesis." (PMID 34830820, 2021).
Ewing sarcoma (continued). "Our work demonstrated that it reduces in a dose- and in a time-dependent manner the expression of Gli1, NR0B1, FOXM1 and VEGFA, some of the EWS-Fli1 target-genes considered as determining factors in the carcinogenesis of Ewing Sarcoma." (PMID 27006472, 2016). "NR0B1 is one the most highly upregulated, direct EWS/FLI targets, and expression of this gene is essential for transformation in Ewing sarcoma cell lines." (PMID 25093581, 2014). "However, when subgroup analyses were performed to address potential confounding influences such as patient sex, zygosity, and chemotherapy our results clearly demonstrate that disease behavior in Ewing sarcoma is not influenced by GGAA-microsatellite polymorphisms at the NR0B1 locus." (PMID 25093581, 2014). "Particularly, inducible shRNA models have been especially advantageous, allowing us to identify some of the genes that participate in the pathogenesis of Ewing tumors, such as cholecystokinin, DKK1 and the orphan nuclear receptor DAX1/NR0B1." (PMID 23750284, 2013). "Numerous independent reports have further validated that NR0B1 is upregulated, a direct EWS/FLI target, and highly expressed in Ewing sarcoma." (PMID 24704979, 2012). "Moreover, in Ewing’s sarcoma, the EWS/FLI fusion protein directly upregulates NR0B1, highlighting the role of alternative oncogenic transcription factors in its regulation." (PMID 40864301, 2025). "Furthermore, NR0B1 is among the most highly upregulated EWS/FLI targets and is essential for oncogenesis in Ewing sarcoma." (PMID 25093581, 2014). "The expression of the selected target genes in Ewing’s sarcoma (CAV1, NR0B1, IGFBP3 and TGFBR2), together with the expression of HIST1H4L, KCNN2, ECRG4 and LDOC1, was then validated in an independent series of PCa with and without ETS gene fusions, as well as in a series of ESFT and ARMS." (PMID 23185447, 2012).
breast carcinoma (21 papers, 2011 to 2025). "NR0B1 is induced by AR-activation in ER+/MCF-7 breast-cancer cells and this causes aromatase down-regulation." (PMID 26894976, 2016). "PLAGL1 has been reported as a possible epigenetically regulated tumor suppressor gene, and NR0B1 (also known as DAX-1) has been repeatedly indicated as a potential target for anticancer therapy in patients with breast cancer." (PMID 40724805, 2025). "Furthermore, HIDEEP reveals that doxorubicin directly targets TOP2A, one of breast cancer-causing genes, and dexamethasone has impacts on TOP2A through HEPs such as ANXA1 → SUMO3 → TOP2A and NR0B1 → UBC → TOP2A." (PMID 29192270, 2017). "NR0B1 sensitizes lung cancer cells to chemotherapy and inhibits their invasive abilities; similar effects might explain the poorer survival outcomes observed here in breast cancer patients upon downregulation of this gene." (PMID 32756008, 2020). "Mammary-glands contain low NR0B1-mRNA and NR0B2-mRNA levels and NR0B1-mRNA is down-regulated in all PAM50 breast-cancer types." (PMID 26894976, 2016). "In conclusion, NR0B1 and NR0B2 are endowed with onco-suppressive properties in breast-cancer." (PMID 26894976, 2016).
X-linked adrenal hypoplasia congenita (18 papers, 2005 to 2025). A X-linked condition characterized by underdevelopment of the adrenal gland and adrenal insufficiency caused by mutation(s) in the NR0B1 gene, resulting in decreased activity of the nuclear receptor protein DAX1, which may be associated with hypogonadotropic hypogonadism. "Over 200 pathogenic variants of NR0B1 have been identified in patients with X-linked AHC, and the complex relationship between genotype and clinical phenotype can contribute to diagnostic delays." (PMID 41300587, 2025). "In male neonates with suspected primary adrenal insufficiency, once 21-hydroxylase deficiency has been excluded by 17-OH progesterone screening, NR0B1-related X-linked adrenal hypoplasia congenita should be considered." (PMID 41300587, 2025). "Loss of function variants in NR0B1 are a known pathogenic mechanisms in individuals with congenital X-linked AHC." (PMID 38075942, 2023). "When Xp21 is lost, NR0B1, which causes X-linked AHC, GK, which causes glycerol kinase deficiency, and in certain circumstances, DMD are also lost (resulting in Duchenne muscular dystrophy)." (PMID 36497046, 2022). "We have previously shown in families where there are 2 brothers with X-linked AHC due to NR0B1/DAX-1 mutations that the second boy is typically diagnosed at a younger age than the first, often because of heightened awareness." (PMID 34258490, 2021). "Extensive diagnostic workup revealed an NR0B1 gene variant confirming the diagnosis of X-linked AHC." (PMID 31263616, 2019). "Mutations in NR0B1 cause X-linked adrenal hypoplasia congenita, with associated HH, whereas mutations in NR5A1 are associated with 46,XY sex reversal or gonadal dysgenesis, and 46,XX is associated with premature ovarian insufficiency." (PMID 31220230, 2019). "X-linked Adrenal Hypoplasia Congenita (AHC) is caused by deletions or point mutations in the NR0B1 (DAX1) gene." (PMID 27656210, 2016). "Mutations in NR0B1 cause X-linked AHC and more than 100 different mutations are reported." (PMID 26523528, 2016). "X-linked adrenal hypoplasia congenita (OMIM # 300200) is a rare disorder, caused by deletions or single nucleotide variants in the NR0B1 (DAX1) gene." (PMID 40013223, 2025). "Congenital X-linked AHC is caused by a mutation in the NR0B1 gene (Xp21.2), which encodes the DAX1 protein, involved in signal transduction and expressed in the adrenal cortex, gonads, hypothalamus, and pituitary glands." (PMID 38075942, 2023). "Disruption of NR0B1 (DAX-1), causing X-linked adrenal hypoplasia congenita (AHC) was found in 7.7% (12/155) of children in the research cohort." (PMID 34258490, 2021). "X-linked Adrenal Hypoplasia Congenita (AHC) is a rare cause of primary adrenal insufficiency due to mutations in the NR0B1 gene, causing a loss of function of the nuclear receptor protein DAX-1." (PMID 31164167, 2019).
lung carcinoma (11 papers, 2016 to 2025). "Additionally, this study may enhance the understanding of the molecular mechanisms associated with NR0B1 in lung cancer progression and drug resistance." (PMID 40864301, 2025). "The differential expression of NR0B1 by gender conforms to the gender difference that has been observed in the prevalence of lung cancer, even when the increase of female lung cancer prevalence is taken into account." (PMID 27281610, 2016). "Additionally, NR0B1 has been implicated in modulating ferroptosis resistance through activation of the c-JUN/NRF2-CBS signaling axis in lung cancer cells, suggesting a complex interplay between NR0B1 and multiple transcriptional regulators." (PMID 40864301, 2025). "Implantation in mice of lung cancer cells A549 harboring depleted NR0B1 further proved that tumor growth was restrained in the absence of NR0B1 and favored RSL3-induced ferroptosis." (PMID 38539832, 2024). "NR0B1 silencing decreased the in vitro invasiveness of the lung cancer cell line A549 and inhibited xenograft growth without affecting cell proliferation." (PMID 34966575, 2021).
primary adrenal insufficiency (10 papers, 2012 to 2025). A hormonal disorder that occurs when the adrenal glands fail to release adequate amounts of glucocorticoids (cortisol), mineralocorticoids (aldosterone, 11-deoxycorticosterone), and androgens (dehydroepiandrosterone) to meet physiologic needs, despite release of ACTH from the pituitary. "The present study suggests that the combination of primary adrenal insufficiency and HH at any age should raise the suspicion of NR0B1 variants, which requires immediate genetic testing." (PMID 41300587, 2025). "To date, more than 100 different mutations in NR0B1 have been described and it has been estimated that 58% of boys with idiopathic primary adrenal insufficiency have mutations in NR0B1." (PMID 22761912, 2012). "Given the presence of Addison’s disease with HH, potential infertility, and family history, the patient was tested for mutation in the DAX-1 (NR0B1) gene." (PMID 28741070, 2017).
congenital adrenal hypoplasia (9 papers, 2012 to 2026). "Two different variants of the NR0B1 gene have been detected in patients with nIHH and concomitant adrenal dysfunction (congenital adrenal hypoplasia and CAH)." (PMID 39010903, 2024). "Two patients with concomitant adrenal diseases (CAH and congenital adrenal hypoplasia) were found to have LP-type mutations in the NR0B1 gene." (PMID 39010903, 2024). "NR0B1 mutation leads to the congenital adrenal hypoplasia (CAP) as a rare X-linked disorder with an estimated prevalence of 1 : 140,000–1 : 1,200,000 in a general population." (PMID 34938333, 2021). "In particular, Nr0b1 was cloned as the gene responsible for X-linked congenital adrenal hypoplasia in humans." (PMID 23131041, 2012).
Infertility (8 papers, 2009 to 2022). "DAX1 has been reported to play a role in testis morphogenesis as Nr0b1-deficient mice are infertile because of an obstruction of the rete testis and efferent ductules by dysregulated proliferation of Sertoli cells." (PMID 35613264, 2022). "The hypogonadotropic hypogonadism may manifest as delayed puberty, impaired spermatogenesis or infertility which is explained by the expression of NR0B1 in the hypothalamus and the anterior pituitary, besides the adrenal glands and the gonads." (PMID 29280740, 2017). "NR0B1 mutations in humans result in HH and infertility rather than disorder in sex differentiation." (PMID 22761912, 2012). "Nonetheless, it has been shown that overexpression of INS in LCs reduces the number of germ cells and gradually leads to infertility in mice, and that insulin induces the expression of DAX1 (officially NR0B1) in LCs, which in turn inhibits testicular steroidogenesis both in vivo and in vitro." (PMID 31505893, 2019).
congenital adrenal hyperplasia (7 papers, 2013 to 2026). Congenital adrenal hyperplasia (CAH) is an inherited endocrine disorder caused by a steroidogenic enzyme deficiency that is characterized by adrenal insufficiency and variable degrees of hyper or hypo androgyny manifestations, depending of the type and the severity of the disease. "The present findings broaden the molecular landscape of NR0B1 variants and underscore the relevance of early genetic testing to differentiate X-hypoAC from congenital adrenal hyperplasia, optimize long-term clinical management, and provide accurate genetic counseling for affected families." (PMID 41876091, 2026). "Congenital adrenal hyperplasia (CAH) is a rare X-linked recessive inherited disease that is considered a major cause of steroidogenesis disorder and is associated with variants or complete deletion of the NR0B1 gene." (PMID 34373561, 2021).
lung adenocarcinoma (6 papers, 2007 to 2025). A carcinoma that arises from the lung and is characterized by the presence of malignant glandular epithelial cells. "In this study, we used multi-omics and wet-lab approaches to explore the correlation between KEAP1 mutations, the methylation status of the NR0B1 promoter, NR0B1 gene expression and survival of patients with lung adenocarcinoma (LUAD)." (PMID 40864301, 2025). "Nuclear Receptor Subfamily 0 Group B Member 1 (NR0B1) was involved in the resistance against anti-cancer drugs and invasion of lung adenocarcinoma cell lines." (PMID 36699376, 2022). "NR0B1 protein was detected in cancerous tissues of more than 50% of human lung adenocarcinoma (ADCA) cases and tended to be expressed in low-differentiated cancerous tissues obtained from males." (PMID 27281610, 2016). "Knockdown of NR0B1 can reduce the tumorigenic and anti-apoptotic potential of lung adenocarcinoma." (PMID 37316840, 2023). "In addition, NR0B1 is ectopically activated in several types of cancers, including endometrial carcinoma, ovarian carcinoma, prostate carcinoma, Ewing's sarcoma, lung adenocarcinoma (ADCA), breast cancer and hepatocellular carcinoma." (PMID 27281610, 2016). "In the present study, we found some genes that are related to drug resistance, such as AKR1C1/C2 and NR0B1, or cancer metastasis, such as TM4SF1, were up-regulated in SP cells of human lung adenocarcinoma A549 cell line." (PMID 18034892, 2007). "Therefore, we acknowledge that the regulatory landscape of NR0B1 is multifactorial, and further studies are warranted to dissect these alternative regulatory mechanisms in the context of KEAP1-mutant lung adenocarcinoma." (PMID 40864301, 2025).
Azoospermia (5 papers, 2015 to 2023). Absence of any measurable level of sperm,whereby spermatozoa cannot be observed even after centrifugation of the semen pellet. "Abnormalities in spermatogenesis (oligo-, azoospermia) may also occur in patients with AHC and NR0B1 (DAX1) mutations." (PMID 27656210, 2016).
cervical carcinoma (5 papers, 2018 to 2024). A carcinoma arising from either the exocervical squamous epithelium or the endocervical glandular epithelium. "In addition, NR0B1 is overexpressed in cervical cancer and promotes cancer cell proliferation via the Wnt/β-catenin pathway." (PMID 34966575, 2021).
hepatocellular carcinoma (5 papers, 2018 to 2024). A malignant tumor that arises from hepatocytes. "Interestingly, NR0B1 was down-regulated in hepatocellular carcinoma tissues and cell lines and overexpression of NR0B1 could inhibit cell proliferation, indicating that it may be a tumor suppressor in hepatocellular carcinoma." (PMID 34966575, 2021). "NR0B1 is a poor prognostic factor in hepatocellular carcinoma (HCC) that enhances sorafenib resistance by activating autophagy and inhibiting apoptosis, suggesting it as a detrimental influence on HCC treatment outcomes." (PMID 39315094, 2024). "BIRC5, SPINK5, SPP1, CACYBP, RAET1E, and NR0B1 were significantly up-regulated, and S100A8 was significantly down-regulated in hepatocellular carcinoma samples based on TCGA-HCC dataset." (PMID 33568167, 2021).
familial glucocorticoid deficiency (4 papers, 2016 to 2025). Familial glucocorticoid deficiency (FGD) is a group of primary adrenal insufficiencies characterized clinically by neonatal hyperpigmentation, hypoglycemia, failure to thrive, and recurrent infections, and biochemically by glucocorticoid deficiency without mineralocorticoid deficiency. "The initial presentation of pathogenic NR0B1 often is associated with a combination of mineral and glucocorticoid deficiency in the neonatal period, and the patient can exhibit delayed puberty." (PMID 41300587, 2025). "Based on the presence of a micropenis and the later onset of hyperpigmentation, along with failed ACTH stimulation test and XY karyotype, we suspected the diagnosis of mutations of NR0B1, CYP11A1, and STAR genes or familial glucocorticoid deficiency (FGD) (MC2R, MRAP, NNT, and AAAS)." (PMID 36407315, 2022).
gonadal dysgenesis (4 papers, 2012 to 2024). A congenital disorder characterized by the presence of extremely hypoplastic gonads preventing the development of secondary sex characteristics. "Xp21 duplications containing the NR0B1 (DAX1) locus have long been known to be associated with XY gonadal dysgenesis (GD)." (PMID 22518125, 2012). "In addition, patients with partial duplications of Xp (including the NR0B1 gene) and chromosome 9p deletions (involving the DMRT1 and DMRT2 genes) may also present with isolated 46,XY complete gonadal dysgenesis (CGD)." (PMID 28836496, 2018).
cryptorchidism (3 papers, 2016 to 2022). The failure of one or both testes of a male fetus to descend from the abdomen into the scrotum during the late part of pregnancy. "None of our four male infants had cryptorchidism nor DAX-1(NR0B1) gene mutation." (PMID 35495001, 2022).